MIR548AA1 (microRNA 548aa-1)
Synonyms: hsa-mir-548aa-1
Gene: MicroRNA gene on chromosome 8 (123,348,034 to 123,348,130, forward strand). Ensembl gene ENSG00000207704.
Homologues: Paralogues in human: MIR548AZ (78% identical), MIR548K (78% identical), MIR548H3 (73% identical), MIR548Z (71% identical), MIR548AY (70% identical), MIR548X2 (69% identical), MIR548AN (67% identical), MIR548F1 (66% identical), MIR548F3 (63% identical), MIR548N (63% identical), MIR548P (63% identical), MIR548X (59% identical), and 13 more.